P4HA2 (prolyl 4-hydroxylase subunit alpha 2)
Diseases named in the same sentence as P4HA2 in open-access papers (continued):
Sharing a sentence is not in itself a finding about the gene and the disease.
cervical carcinoma (continued). "Functionally, we demonstrated that P4HA2 knockdown attenuated cell proliferation, migration and invasion of cervical cancer cells." (PMID 32226497, 2020). "To further explore the function of P4HA2 in cervical cancer progression, we evaluated three different shRNAs targeting P4HA2 (P4HA2-shRNA-1/2/3) in SiHa and HT-3 cells, which had the highest levels of P4HA2." (PMID 32226497, 2020). "Mechanistically, bioinformatics analysis indicated EMT process was involved and we further validated that P4HA2 promoted cervical cancer progression and metastasis via inducing EMT." (PMID 32226497, 2020). "Collectively, these results demonstrated that P4HA2 knockdown was capable to suppress the tumorigenesis of cervical cancer in vivo." (PMID 32226497, 2020). "Consistently, western blot results further demonstrated the higher expression levels of P4HA2 protein in pairs cervical cancer tissues and cervical cancer cell lines compared with those in matched non-neoplastic tissues and normal control cell line." (PMID 32226497, 2020). "In this study, we found that P4HA2 was markedly upregulated in cervical cancer and high P4HA2 expression predicted poor clinical outcomes based on tissue microarray analysis." (PMID 32226497, 2020). "The correlation of the P4HA2 expression levels and prognosis of cervical cancer patients were analysed in TCGA cervical cancer cohort and tissue microarray (TMA) cohort." (PMID 32226497, 2020). "Functionally, silencing P4HA2 suppresses the proliferation and metastatic ability of cervical cancer in vitro and in vivo." (PMID 32226497, 2020). "Using both in vitro cell line and in vivo xenograft tumor model, we found knockdown P4HA2 inhibited cervical cancer development and metastasis." (PMID 32226497, 2020). "Mechanistically, bioinformatics analysis revealed that epithelial-mesenchymal transition (EMT) was involved in cervical cancer progression regulated by P4HA2 and we further confirmed knockdown P4HA2 suppressed the EMT process." (PMID 32226497, 2020). "Collectively, these data suggest that silencing P4HA2 can attenuate the aggressive activities of cervical cancer cells, at least in part, by regulating the EMT process." (PMID 32226497, 2020). "The expression levels of Col1A1, Col3A1, Col4A1 and HIF-1α were positively correlated with P4HA2 levels in TCGA cervical cancer cohort (P < 0.001)." (PMID 32226497, 2020). "In addition, P4HA2 can also enhance the glycolysis of cervical cancer cells to accelerate the tumor process." (PMID 40347062, 2025). "In addition, a study on cervical carcinoma reported that high P4HA2 expression was correlated with advanced FIGO stage, LN metastasis, and positive LVI." (PMID 38522060, 2024). "Notably, P4HA2 has been reported to be a prognostic biomarker in cervical cancer, which was increased expression in cervical cancer tissues compared with the adjacent normal tissues, and related to poor prognosis." (PMID 35657977, 2022). "Taken together, P4HA2 might serve as a novel prognostic biomarker and promising therapeutic target in cervical cancer." (PMID 32226497, 2020). "P4HA2 were mostly distributed in cell cytoplasm of cervical cancer cells." (PMID 32226497, 2020). "In addition, we demonstrated that knockdown P4HA2 inhibited the proliferation, migration and invasion of cervical cancer cells in vitro and suppressed cervical tumor growth in vivo." (PMID 32226497, 2020). "Mechanistically, we revealed the positive association between highP4HA2 expression and activation of the EMT process, indicating that P4HA2 might play an oncogenic role in cervical cancer progression by inducing EMT." (PMID 32226497, 2020). "Taken together, the data suggest that P4HA2 might serves as an oncogene via activating the EMT process in cervical cancer." (PMID 32226497, 2020).
cervical carcinoma (continued). "Our data revealed a close positive correlation between the expression of P4HA2 and collagen biosynthesis-related genes (Col4A1, Col5A1 and Col6A1) in cervical cancer, which is also consistent with a previous report of a positive correlation between collagen biosynthesis and P4HA2 in breast cancer." (PMID 32226497, 2020). "Conclusion: our results suggest that P4HA2 functions as an oncogene in promoting cervical cancer cell proliferation, migration and invasion by inducing EMT, which might be a promising prognostic factor and therapeutic target for cervical cancer." (PMID 32226497, 2020). "Mechanistically, P4HA2 plays an oncogenic role by promoting the EMT process in cervical cancer." (PMID 32226497, 2020). "Furthermore, Transwell migration assays showed that the relative migration cells of cervical cancer cells were remarkably decreased after P4HA2 knockdown." (PMID 32226497, 2020). "However, the functional roles of P4HA2 in cervical cancer progression remain to be elucidated." (PMID 32226497, 2020). "For example, P4HA2 induced EMT and promote tumor growth, migration, and invasion in cervical cancer and glioma, while in prostate and pancreatic cancer, it served as a tumor suppressor." (PMID 36998462, 2023). "The expression of P4HA2 increased in head and neck squamous cell carcinoma (HNSCC), Oral Squamous Cell Carcinoma (OSCC), cervical cancer and other cancers." (PMID 35111402, 2022). "Thus, P4HA2 might be a promising therapeutic target for cervical cancer patients." (PMID 32226497, 2020). "We found that cervical cancer patients with high P4HA2 expression had significant lower probabilities of OS and RFS in comparison with patients with low P4HA2 expression." (PMID 32226497, 2020). "We first investigated the expression levels of P4HA2 in 36 pairs of cervical cancer tissues and matched non-neoplastic counterparts." (PMID 32226497, 2020). "QRT-PCR results showed that P4HA2 was significantly upregulated in cervical cancer tissues compared with adjacent non-tumor tissues." (PMID 32226497, 2020). "We subsequently detected the expression levels of EMT process-related markers in cervical cancer cells transfected with P4HA2-sh-2 or negative control." (PMID 32226497, 2020). "Taken together, our results suggest that P4HA2 functions as an oncogene in promoting cervical cancer cell proliferation, migration and invasion by inducing EMT, which might be a promising prognostic factor and therapeutic target for cervical cancer." (PMID 32226497, 2020). "To explore the underlying mechanisms by which P4HA2 knockdown inhibits tumor growth of cervical cancer, we next conducted KEGG pathway enrichment analysis and Gene Ontology (GO) enrichment analysis of the top 800 genes with the highest P4HA2 correlation coefficients in TCGA cervical cancer cohorts." (PMID 32226497, 2020).
glioma (10 papers, 2020 to 2026). A benign or malignant brain and spinal cord tumor that arises from glial cells (astrocytes, oligodendrocytes, ependymal cells). "Another study showed that the transcription factor CEBPB promoted the development of isocitrate dehydrogenase 1 wildtype (IDH1 wt) gliomas by upregulating P4HA2 protein in glioma cells at the transcriptional level." (PMID 40347062, 2025). "Prolyl-4-hydroxylase subunit 2 (P4HA2), a collagen modification enzyme, exhibits higher transcriptional levels in glioma samples compared to normal brain tissue, correlating with glioma grading and patient survival." (PMID 38732975, 2024). "High levels of P4HA2 correlate with poor prognosis in glioma, and P4HA2 knockdown blocks glioma cells proliferation, migration and acquisition of EMT-like phenotypes." (PMID 32500033, 2020). "Additionally, immunohistochemical staining showed higher P4HA2 levels in Breast, Lung, Colon, Liver, Ovary, and Glioma tissue sections compared to normal tissues." (PMID 41424847, 2026). "In addition, P4HA2 is also involved in the resistance to temozolomide, the primary therapeutic drug for glioma." (PMID 40347062, 2025). "The main transcriptional P4HA2 level was found to be higher in glioma samples compared to normal brain tissue, and this correlates with glioma grading and patient survival; moreover, a P4HA2 knockdown significantly decreased cellular invasion and migration in Matrigel." (PMID 36980765, 2023). "One study on glioma cells in vitro showed knockdown of P4HA2 inhibited proliferation, migration, invasion, and EMT-like phenotype of glioma cells." (PMID 38522060, 2024). "Three top cancer types, BRCA, LGG (lower grade glioma) and THCA, exhibited most strongly correlation between P4HA2 with immune cells (P < 0.0001)." (PMID 34249930, 2021). "Prolyl-4-hydroxylase subunit 2 (P4HA2), as one of the hub genes interacted the collagen members above, was reported to play an important role in tumor proliferation, migration, invasion, and epithelial-to-mesenchymal transition (EMT) in gliomas." (PMID 34868960, 2021). "Although this correlation was not previously investigated in CRC, a previous study in glioma reported that expressions of SNAl1 and SLUG are regulated by P4HA2 either at transcriptional or translational level." (PMID 38522060, 2024).
hepatocellular carcinoma (10 papers, 2020 to 2025). A malignant tumor that arises from hepatocytes. "Recently, dysregulation of P4HA2 has been implicated in various types of cancers, such as oral squamous cell carcinoma, breast cancer, hepatocellular carcinoma, and pancreatic cancer." (PMID 38522060, 2024). "In hepatocellular carcinoma cells, quercetin treatment downregulated proline 4-hydroxylase (P4HA2) and inhibited the PI3K/Akt/mTOR signaling pathway, leading to pronounced apoptosis." (PMID 40808836, 2025). "Studies have reported the accumulation of P4HA2 in cancer cells and its contribution in accelerating collagen deposition and metastatic dissemination in vivo, such as lung adenocarcinoma, hepatocellular carcinoma, prostate cancer, cervical cancer, glioblastoma and so on." (PMID 40379610, 2025). "P4HA2 is correlated to liver fibrosis and hepatocellular carcinoma (HCC)." (PMID 32500033, 2020). "However, the relationship between quercetin and cell apoptosis, as well as the impact of P4HA2 in this connection, has not yet been specified in hepatocellular carcinoma(HCC)." (PMID 40347062, 2025).
oral cavity squamous cell carcinoma (8 papers, 2014 to 2025). A squamous cell carcinoma arising from the oral cavity. "As P4HA2 regulates the PI3K/AKT signaling pathway in oral squamous cell carcinoma, we detect whether P4HA1 can regulate the PI3K/AKT signaling pathway via P4HA2 in CRC." (PMID 41469036, 2025).
lung carcinoma (7 papers, 2013 to 2025). "High P4HA2 expression indicated a poor prognosis and served as an independent prognostic risk factor in lung cancer." (PMID 36403427, 2022). "Collagen prolyl 4-hydroxylase(P4H) is a dioxygenase that catalyzes 4-hydroxylation of proline, although it has been reported that P4HA2 inhibits the growth of lung cancer by enhancing mTOR stability." (PMID 39920992, 2025). "This explains why P4HA1 is better characterized for its role in lung cancer, whereas P4HA2 is well known for its role in glioma and cervical cancer." (PMID 39329988, 2024). "We should note that restoring RASSF1A expression in lung cancer cells activates the Hippo pathway leading to the inhibition of YAP-mediated transcription of P4HA2, cell stemness, ECM stiffness, and metastasis." (PMID 36826019, 2023). "We also found that silencing of RASSF1C in lung cancer cells resulted in the down-regulation of P4HA2 and PLOD2." (PMID 36826019, 2023). "Consistent with RT-PCR analysis, lung cancer cells overexpressing RASSF1C had increased P4HA2, PLOD2, and collagen I protein levels." (PMID 36826019, 2023). "Three genes, P4HA2, TJP3, and BAIAP2L1, have been shown to be associated with lung cancer B lymphocytes in situ." (PMID 34575089, 2021). "The role of P4HA2 in lung cancer deserves additional and more detailed studies." (PMID 39329988, 2024). "Recently published work showed that collagen hydroxylation promotes EMT in A549 lung cancer cells through DNA and histone demethylation/hydroxylation, and knockdown of P4HA2 in A549 lung cancer cell lines resulted in down-regulation of H3K9me2 and H3k36me3 and decreased cell migration." (PMID 36826019, 2023). "We were able to identify the P4HA2 and PLOD2 genes as RASSF1C target genes in both breast and lung cancer cells." (PMID 36826019, 2023). "We have assessed P4HA2 and PLOD2 expression in vivo using lung tissue derived from an orthotopic metastasis model using lung cancer cell lines A549 and H1299." (PMID 36826019, 2023). "P4HA2 and PLOD2 expression was confirmed in breast and lung cancer cells overexpressing RASSF1C by RT-PCR." (PMID 36826019, 2023). "We found that P4HA2 and PLOD2 were up-regulated in both breast and lung cancer cell lines, T47D and H1299, respectively." (PMID 36826019, 2023). "RASSF1C up-regulation of P4HA2 and PLOD2 expression in both breast and lung cancer cells was confirmed by RT-PCR analysis." (PMID 36826019, 2023). "We find that lung cancer cells with RASSF1A promoter methylation display constitutive nuclear YAP1 accumulation and expression of prolyl 4‐hydroxylase alpha‐2 (P4HA2) which increases collagen deposition." (PMID 31268606, 2019). "We found overexpressing PIWIL1, like RASSF1C, promotes lung cancer cell migration/invasion and that PIWIL1 overexpression resulted in increased expression of P4HA2, PLOD2, and collagen I protein levels suggesting that PIWIL1 could play a role TME remodeling." (PMID 36826019, 2023). "In this regard, we report that RASSF1C and PIWIL1 may promote lung cancer cell metastasis through modulation of tumor microenvironment/ECM through regulation of Collagen I, P4HA2, and PLOD2 gene expression." (PMID 36826019, 2023). "In support of this idea, we found that overexpression of PIWIL1 promotes lung cancer cell migration/invasion, which is consistent with published reports; and cells overexpressing PIWIL1 display increased protein levels of P4HA2, PLOD2, and collagen I to some extent." (PMID 36826019, 2023). "Thus, our findings suggest that the RASSF1C-PIWIL1 pathway could potentially promote lung cancer microenvironment/ECM remodeling to induce lung cancer cell stemness and metastasis, in part, via modulation of P4HA2 and PLOD2 expression." (PMID 36826019, 2023). "We do not know if the inhibition of lung cancer cell migration/invasion by piR-35127 and piR-46545 may involve modulation of P4HA2 or PLOD2 expression." (PMID 36826019, 2023).
B-cell lymphoma (5 papers, 2023 to 2025). "P4HA2 is a member of prolyl 4-hydroxylase family, the latter were detected down-regulated in almost all common B-cell lymphoma types and were associated with methylation of CpG islands in lymphomas and may be useful in differentiating disease subtypes." (PMID 37248456, 2023). "Our findings highlight the role of P4HA2-mediated hydroxylation in modulating Hh signaling and propose a novel stromal-targeted therapeutic strategy for B-cell lymphoma." (PMID 38909089, 2024). "Despite these observations, the specific role of stromal P4HA2 in the progression of B-cell lymphoma remains ambiguous and warrants further investigation." (PMID 38909089, 2024). "The findings presented in this study unveil a previously unrecognized role of P4HA2 in the regulation of the Hh signaling pathway and its consequential impact on B-cell lymphoma tumorigenesis via a paracrine mechanism." (PMID 38909089, 2024). "Our murine model with P4ha2 knockout demonstrates the physiological relevance of P4HA2 in B-cell lymphoma progression, highlighting its crucial role in the stromal microenvironment." (PMID 38909089, 2024). "We constructed a B-cell lymphoma mouse model to demonstrate that P4HA2 is expressed in stromal cells to promote B-cell lymphoma progression via regulating the Hh signaling." (PMID 38909089, 2024). "However, in most malignancies such as bladder cancer, ovarian cancer, and B-cell lymphoma, tumors with high expression of P4HA2 have been observed to have a higher degree of malignancy." (PMID 39920992, 2025). "In B-cell lymphoma, P4HA2 hydroxylates carabin protein, promoting its degradation." (PMID 38951593, 2024). "Integrating findings from a prior study wherein P4HA2 was identified as promoting B-cell lymphoma in tumor cells, and the current study revealing its high expression in the stromal fibroblasts of B-cell lymphoma, emphasizes P4HA2 as a promising target for therapeutic intervention." (PMID 38909089, 2024). "Further investigations into the specific P4HA2 inhibitors may offer an attractive new therapeutic strategy for B-cell lymphoma." (PMID 38909089, 2024). "The identification of P4HA2 as a key player in stromal fibroblasts emphasizes its potential as a therapeutic target for disrupting the tumor microenvironment and influencing Hh signaling in B-cell lymphoma." (PMID 38909089, 2024). "SUFU can be hydroxylated by the complex of P4HA2 and KIF7, which inhibits its function and amplifies Hh signaling in B-cell lymphoma." (PMID 40170839, 2025). "In conclusion, our study uncovers a novel regulatory axis involving P4HA2, KIF7, and SUFU in the Hh signaling pathway, shedding light on the intricate mechanisms governing B-cell lymphoma tumorigenesis." (PMID 38909089, 2024). "Collectively, our observations suggest that P4HA2, along with the proline hydroxylation of SUFU, plays crucial roles in promoting B-cell lymphoma progression through a paracrine signaling transduction mechanism." (PMID 38909089, 2024). "Notably, P4HA2 was highly expressed in tumor stromal fibroblasts in DLBCL samples, which promoted us to investigate the role of the P4HA2-Hh axis in stromal cells promoting B-cell lymphoma tumorigenesis." (PMID 38909089, 2024).
bladder cancer (5 papers, 2024 to 2025). "Research on P4HA2 has mainly concentrated in the fields of bladder cancer, prostate cancer, melanoma and other diseases." (PMID 40379610, 2025). "In erdafitinib-resistant bladder cancer cells, high levels of prolyl 4-hydroxylase subunit alpha 2 (P4HA2) stabilize hypoxia inducible factor 1α (HIF-1α), which activates downstream target genes and lowers ROS levels in bladder cancer." (PMID 38982494, 2024). "The discovery of P4HA2 provides a potential and valuable target for targeted therapy of acquired resistance in bladder cancer." (PMID 39421736, 2024). "Previous studies have reported that, P4HA2-mediated stabilization of HIF-1α promotes FGFR3 expression and increases erdafitinib resistance in bladder cancer." (PMID 40379610, 2025). "used RNA-seq for whole transcriptome analysis and intercellular space analysis to discover that P4HA2 stabilizes HIF-1α protein to activate genes downstream, thereby resulting in decreased levels of ROS in bladder cancer cells." (PMID 39421736, 2024).